CD4 (CD4 molecule)
Diseases named in the same sentence as CD4 in open-access papers (continued):
Sharing a sentence is not in itself a finding about the gene and the disease.
infection (continued). "Virion incubation with 10% semen in fact increased the infection of CD4+ T cells by 3.1-fold." (PMID 38501840, 2024). "Furthermore, to confirm productive infection of ASDCs via CD4/CCR5, we demonstrated that the CCR5 inhibitor maraviroc was able to completely block the ability of ASDCs to mediate second phase transfer." (PMID 38924030, 2024). "As a result, more HIV is replicated at an increased pace, and most CD4+ T-cells are lost; this may result in severe infection." (PMID 39335628, 2024). "Additionally, like CD8+ T cells, a population of CD4+ T cells also persist in the upper dermis after the resolution of infection." (PMID 39599904, 2024). "Interestingly, among previously non-infected individuals, those with subsequent breakthrough infections had significantly lower levels of vaccine-induced neutralizing activity and CD4 T cells." (PMID 38594497, 2024). "Additionally, these results can be explained by the preferential upregulation of IL-18R on CD4+ T cells by day 8 post-infection." (PMID 39446964, 2024). "The risk of infection particularly increases throughout the treatment course for people with HIV due to the combination of myelosuppression and potentially already reduced CD4 counts." (PMID 38611075, 2024). "Our approach could also be extended in principle to antigen-specific CD4+ T cells and other infections beyond SIV." (PMID 38885329, 2024). "HLA-DR+ CD4 T cells could be a useful marker for identifying effector T cells and monitoring immune responses in many infection and vaccination models." (PMID 39045270, 2024). "Specifically, male, age over 30, heterosexual infection, long-term infection, CRF01_AE subtype, and pre-treatment CD4 T cell counts < 350/μL, clinical III and IV stage, and longer initiated treatment time were identified as risk factors impeding CD4+T lymphocyte recovery." (PMID 38994006, 2024). "M. tuberculosis-infection in AM is efficiently controlled by T cells, particularly by CD4 T cells." (PMID 38977711, 2024). "Notably, CD4+ T cells from C. rodetium-infected VillinCre MHCIIflox/flox mice exhibited reduced production of IL-22 and IL-17A during the late phase of infection." (PMID 39379604, 2024). "Furthermore, administration of the anti-α4β7 antibody to SIV-infected RMs undergoing ART improved infection outcomes, CD4+ T-cell preservation, and virus control." (PMID 38932264, 2024). "The TB was the most typical OI infection in both cohorts, which in part may be explained by a comparable proportion of those with low CD4 cell counts being at baseline." (PMID 38299523, 2024). "However, that difference between adults and juveniles disappeared when cells were stimulated with PHA, or when isolated CD4 cells were used for infection." (PMID 39006742, 2024). "This suggests that models of incidence or date of infection based on CD4 decline may be distorted by this situation." (PMID 39691355, 2024). "However, peripheral blood CD4-ATP levels were useful in differentiating between rejection and infection, being lower in the infection group." (PMID 39594991, 2024). "Notably, at days 14, 21, and 28 post-infection, the number of pulmonary CD4+ T lymphocytes was significantly higher in Balb/c mice compared to Card9em1Sq mice." (PMID 38921420, 2024). "Overall, these results may suggest the SARS-CoV-2-reactive CD4+ T cell responses in a proportion seronegative children could be due in part to cross-reactive T cell immunity resulting from prior infection with common cold HCoV-HKU1." (PMID 38235336, 2024). "In an M.tb model of infection, fewer M.tb colony‐forming units (CFUs) were observed in the lungs of Rag1‐KO mice that received mito‐transferred naïve CD4+ T cells (p = 0.004) or non‐manipulated naïve CD4+ T cells from old mice (p = 0.01), compared to control infected Rag1‐KO mice." (PMID 37990641, 2024). "Lower CD4+-T-cell numbers were associated with a slight effect on the occurrence of infections (Est.=-0.0014) but failed to reach statistical significance (p=0.148)." (PMID 37152008, 2023).
infection (continued). "Moreover, the heterologous ZF2001 group displayed significantly lower levels of CD4 counts but similar CD8 counts after breakthrough infection." (PMID 38140668, 2023). "In contrast, infection, producing high levels of antigen and PR recognition signals through the effector checkpoint, induces the greatest functional diversity, additional more potent CD4 memory subsets, and memory that is resident in the tissues of infection as well as SLO." (PMID 38152398, 2023). "Single-cell RNA sequencing of CD45+ cells from the brain revealed colocalization of viral transcripts within CD4 clusters and significant activation of antiviral molecules and specific effector programs within T cells, indicating CNS CD4 T cell engagement during infection." (PMID 38060615, 2023). "This study did not observe an increased risk of omicron variant infection among PLWH with lower CD4 counts." (PMID 37964230, 2023). "In the first week after infection, FoxP3 expression is lower while T-bet expression is higher on activated CD4+ T cells in μMT mice; however, we found expression of FoxP3 and T-bet was similar in activated CD4+ T cells from B cell MHCII deficient mice and control animals one week post-infection." (PMID 37721965, 2023). "HDACi-independent replication of unintegrated HIV has also been demonstrated in the infection of blood resting CD4 T cells stimulated with common gamma-chain cytokines, a condition mimicking HIV infection and replication in lymphoid tissues where cytokines are found to be highly enriched." (PMID 37345240, 2023). "Restricted cubic spline (RCS) was applied to assess the non-linear association between Bh infection risk and CD4+ T cell counts, HIV VL, and duration of interruption in highly active antiretroviral therapy (HARRT)." (PMID 37697423, 2023). "Moreover, the adaptive immune system, which is the most important for prevention of bacterial translocation and gut-derived infection, will also be compromised with both CD4 and CD8 T cells perturbed." (PMID 37768071, 2023). "The downregulation of SDF-1α in our study might indicate that SIV tends to infect CD4+ T cells more efficiently due to the availability of CXCR4 receptors at the early stage of infection." (PMID 36851142, 2023). "Interestingly, IRF7 was shown to impair early splenic CD4+ Th1 cell activation, thereby promoting infection by blood-stage Plasmodium." (PMID 37251373, 2023). "Furthermore, Tat-mediated T/F LTR transcriptional activity significanly correlated positively with viral load set point and viral load; and negatively with CD4 T cell counts at one year post infection (all p<0.05)." (PMID 37307292, 2023). "Additionally, the ratio of CD4+/CD8+ T cells in peripheral blood tended to gradually decrease with prolonged infection, indicating the possibility of persistent infection." (PMID 37587524, 2023). "Consistent with the hypothesis that CD4-sCoV-2 interaction is required for infection, we observed that pre-incubation with soluble CD4 (sCD4) completely blunted viral load in CD4+ T cells exposed to SARS-CoV-2." (PMID 37523305, 2023). "The LN L/S ratio less than 2 was known as malignant enlargement of LNs, so this relationship between CD4+T cell and LN L/S ratios may be explained as the worse immune status resulting in a heavier infection." (PMID 38148912, 2023). "Thus, up-regulated PD-1 MFI occurred especially on CD4+ T cells, reaching a 1.3, 2.1 and 3.7-fold increase at days 30, 60 and 90 after infection, respectively, as compared to uninfected controls." (PMID 37691941, 2023). "We were interested in whether rates of viral sequence diversification (i.e. APD slope) varied significantly by individual, gene region, mode of infection, set-point viral load, or rate of CD4+ T cell decline." (PMID 38117834, 2023). "The CD4+ T helper (Th) cells are well known for their role in the development, affinity maturation and isotype switching of antibody responses as well as in the generation of memory B cells following infection." (PMID 37809062, 2023).
infection (continued). "Upon infection with a sarbecovirus, vaccine-induced CD4+ T cells may improve CD8+ T cell and B cell responses specific to the incoming virus." (PMID 37707962, 2023). "In the intestines, the expression of adaptive immune-related genes (C3, TCR α, MHC I, MHC II, CD4, CD8, IgM, IgZ and IgD) was higher in immunized groups after 2 times vaccination, and most of them were also significantly up-regulated in the vaccinated groups post infection, except for CD4 and TCR α." (PMID 36969197, 2023). "Previous studies have shown that the initial antigen dose can have an effect on the outcome of infection with T. muris and that low level of infection can have a significant effect on the polarization of the CD4 response by producing high amount of Th2 cytokine." (PMID 37956181, 2023). "Considering that CD209+ DCs promote HIV-1 trans-infection of CD4+ T cells via cell–cell contacts, we speculated that B8-dIgA1 and B8-dIgA2 might not be able to block the similar process for SARS-CoV-2." (PMID 37542391, 2023). "It thus appears that a complex response to BTV is taking place in CD4+ T cells at day 7pi, although PD1-PD-L1 pathway enrichment and DEG expression is indicating that CD4+ T cell activity could be limited by the infection." (PMID 37920474, 2023). "Prior infection with M. abscessus afforded the highest level of protection against M. abscessus challenge in the lung, and immunity was characterised by a greater frequency of pulmonary cytokine-secreting CD4+ T cells compared to BCG vaccination." (PMID 37631881, 2023). "Thus, although the serological cross-reactivity against BA.1 after infection with the ancestral strain was higher in seropositive children in comparison with adults, the CD4 T cell response against BA.1 seems to be maintained better in adults." (PMID 37051428, 2023). "IL‐27 may directly modulate precursor memory CD4+ T cells as observed in the gene expression patterns during acute infection." (PMID 37855243, 2023). "Consistent with the role for IL-17A, we observed that removal of CD4+ T cells or macrophages and neutrophils (individually or double depleted) from vaccinated mice just prior to infection rendered them unable to control infection." (PMID 37749129, 2023). "One of the factors that may have contributed to the differences observed between the ability to induce bnAbs in children and adults is that, in the early stages of infection, children have much higher viral loads and CD4+ cell counts than adults." (PMID 38276667, 2023). "Taken together, these findings suggest one or more Bcl6 expressing CD4+ T cell populations may be necessary for efficient control of infection, or that outgrowth of TReg in CD4CreBcl6fl/fl mice drives enhanced susceptibility to challenge." (PMID 37721965, 2023). "In younger birds, CD4+TGFβ+ cells were only present in the BF from 28dpi, however, these cells infiltrated the BF earlier in older birds (present from 7dpi following 228E infection, and from 14dpi following F52/70 infection)." (PMID 37744374, 2023). "A decrease in the number of circulating CD4+ and CD8+ T cells may increase the risk for infections in people with SCI." (PMID 36367185, 2023). "Notably, at 12 days post-infection, we observed a higher frequency and greater number of CD4+ T cells producing IFN-γ in the spleen of CKO mice compared to WT mice." (PMID 37908369, 2023). "Thus, while we were limited in availability of samples, as proof of principle, HIV demonstrably establishes a small reactivatable population of latently infected cells by infection of CD4+CD25– resting T cells in Fiebig I." (PMID 37733443, 2023). "Furthermore, a gradual dose-dependent increase was observed in the CD4 + /CD8 + T cell ratio during the early stages of infection." (PMID 38072840, 2023). "These factors are also involved in the migration of CD4 T cells in the early stage of infection." (PMID 38036985, 2023).
infection (continued). "FoxP3 expression on CD44+CD4+ T cells was significantly decreased among μMT animals compared to WT at one- and two weeks post infection, suggesting B cells may drive TReg differentiation in response to Brucella." (PMID 37721965, 2023). "However, the development of a CD4+ TFH cell response that promotes effective and long-lasting parasite-specific protective Ab results from multiple competing mechanisms orchestrating CD4+ T cell differentiation during infection." (PMID 38001069, 2023). "Since IGRAs rely on functional CD4 T-cell responses, we next asked whether antibody responses could provide a more sensitive marker of Mtb exposure or infection in PLWH." (PMID 36870197, 2023). "Kim and Perelson hypothesized that viremia during the later phases was due to reactivation of infection from latently infected memory CD4 T cells specific to different antigens at different time points." (PMID 37896896, 2023). "It has been demonstrated that Th17 cells could mediate protection against Mycobacterium tuberculosis infection, probably by promoting CD4+ T cell recruitment to pulmonary sites of infection and accelerating pathogen clearance." (PMID 37337226, 2023). "However, V→D mice depleted of CD4+ T cells that received HK ZNF2oe or HK H99 vaccines at the high dose still succumbed to the infection by DPI 50, with the median numbers of survival days being 27 and 32, respectively." (PMID 37338404, 2023). "In addition to their role in conferring “help” for antibody responses, effector CD4+ T cells (T helper cells) have been reported to be essential for mounting an effective memory CTL response during a secondary infection." (PMID 37344886, 2023). "Thus, CD4+ T cells appear to be the principal IFN-γ-producing cells at the initial infection site and are crucial to the control of T. cruzi at the site of entry." (PMID 36695605, 2023). "In addition, four models identified the top three variables with predictive value for Bh infection as CD4+ T immunological status, HIV virological status, and treatment interruption." (PMID 37697423, 2023). "Both ɣδ and CD4+ T cell infiltrates were significantly increased in the brains of IL-10 KO mice at days 7 and 14 post-infection, respectively, which when combined with the significant reduction in G-MDSCs suggests a transition in the inflammatory milieu in the absence of IL-10." (PMID 37179295, 2023). "Lactiplantibacillus plantarum 0111 oral pretreatment up-regulates ISG transcription 7 days after H9N2 infection while elevating CD3+CD4+TNF-α+T lymphocyte percentage and CD3+CD8+TNF-α+T lymphocyte percentage in the spleen and enhancing adaptive immunity to the virus." (PMID 37928517, 2023). "Heterogeneous clones of CD4-expressing T helper cells are generated during MHV68 infection." (PMID 37065193, 2023). "Likewise, CD69+CD4+lo T cell levels (p<0.01) PD-1+CD4+lo T cell levels and (p<0.001) were significantly higher in all infected groups whereas the levels of ICOS+CD4+lo T cells were only significantly higher in chronic HBV (p<0.01) infection." (PMID 37163092, 2023). "Similarly, previous studies found that Th1 cytokines play an important role in eliminating ORFV infection, and the increase of CD4+cells can also help the body eliminate ORFV." (PMID 37026014, 2023). "A fraction (f) of new infections of target cells (i.e., CD4 T cells) result in latency." (PMID 37896896, 2023). "However, there were significant increases in the percentages of CD4+ T cells and CD4+ Tem cells in spleens from LAG3-KO mice after 12 weeks of infection." (PMID 37172058, 2023). "Finally, the depletion of CD4+ T cells before infection increased mortality in female mice, indicating that CD4+ T cells play a protective role against CVB3 in our model." (PMID 38274806, 2023).
infection (continued). "Taken together, these results clearly show that an impaired selection and maintenance of Tconv CD4+ T-cells in the lymphoid organs of B6.I-103 mice is independent of contact with mycobacteria, suggesting that their response to infection is intrinsically impaired." (PMID 37426653, 2023). "Extensive literature exists on the many blocks to infection of resting CD4+ T cells in vitro that implies that there are critical differences between CD4+CD25– T cells in vitro and resting T cells in LT in vivo that enable the resting cells to support HIV infection." (PMID 37733443, 2023). "Overall, these results indicate SARS-CoV-2-reactive CD4+ T cell responses in seronegative children could be due in part to cross-reactive T cell immunity resulting from prior infection with common cold HCoV-HKU1." (PMID 37292954, 2023). "Nevertheless, it is important to note that in the setting of preventative vaccines, the use of novel epitopes identified with this system may provide better T cell help for a neutralizing antibody response that would prevent any infection of CD4+ T cells." (PMID 37058141, 2023). "Furthermore, such an infection leads to the activation of CD4 T cells reactive to both heart tissue and the bacteria." (PMID 37759652, 2023). "Of particular importance in the establishment and maintenance of the latent viral reservoir is the intercellular transfer of HIV-1 from professional antigen-presenting cells (APCs—monocytes/macrophages, myeloid dendritic cells, and B lymphocytes) to CD4+ T cells, termed trans-infection." (PMID 38140588, 2023). "In the absence of treatment, the development of neutralization breadth in adults has been associated with several clinical factors, including time since infection, high virus load, the presence of normalized B-cell subpopulations, and early decline in circulating CD4+ T cells." (PMID 38276667, 2023). "Indeed, challenge infection with Tc led to significant expansion of effector CD4+ and CD8+ T cells and production of cytotoxic molecules (IFNγ, PRF1, GZB) by both CD4+ and CD8+ effector T-cell subsets in vaccinated (vs. non-vaccinated) pregnant mice." (PMID 38104118, 2023). "Interestingly, acquired resistance is intact in B cell–deficient mice, blocked in MHCII-deficient mice, and ablated in mice treated with anti-CD4 antibody during primary infection." (PMID 37638887, 2023). "The observation that DENV–specific CD4 EMRA T cells expand with repeated infections suggests that a high-dose/repeated antigen exposure may be critical for the development of such cells." (PMID 37199415, 2023). "Productive infection and CD4+ T cell activation are additional important factors to consider." (PMID 38156317, 2023). "In contrast to Th17 cells, IFN-γ+ and TNF-α+ CD4+ Th1 cells were present in roughly similar frequencies in spleen and colon of Irf4+/+ and Irf4-/- mice under steady state conditions as well as following infection." (PMID 37469513, 2023). "Could the initial events in HIV infection be like those in SIV infection, in which the preponderant target cell availability of resting CD4+ T cells dictates establishment of productive infections in HIV-infected resting T cells?" (PMID 37733443, 2023). "Notably, the function of T lymphocytes is disrupted during a natural infection, modulating the CD4 T cell immune response and migration in vivo." (PMID 38069232, 2023). "CD4+ T cells, known as T helper (Th) cells, have multiple functions, including recruitment of cytotoxic T cells to sites of infection, coordinating the humoral antibody response (B cells), and regulating both innate and adaptive immune cell activation and proliferation." (PMID 37239997, 2023). "Taken together, we show that GPI-scFv X5 may be a promising approach for HIV-1 prevention and therapy by restricting HIV-1 cis- and trans-infection mechanisms of CD4+ cells." (PMID 37781368, 2023).